TNF (tumor necrosis factor)
Diseases named in the same sentence as TNF in open-access papers (continued):
Sharing a sentence is not in itself a finding about the gene and the disease.
glioblastoma (continued). "In addition, other investigators showed that co-treatment of ebselen with tumor necrosis factor α (TNF-α) in glioblastoma cells resulted in increased sensitivity to TNF-α and increased apoptosis." (PMID 33498364, 2021). "The integral activation of TNF‐α/NF‐κB suggested that it may be involved in glioblastoma progression." (PMID 31691497, 2020). "Our observations could be important for developing possible correction methods of impaired cytotoxic DC activity derived from glioblastoma patients against autologous tumor cells sensitive to TNFα/TNF-R1-dependent lysis." (PMID 32326230, 2020). "Therefore, it can be suggested that the effect of rIL-2 on TNFα expression in IFN-DCs from glioblastoma patients is implemented at the post-transcriptional level via a protein kinase-dependent mechanism." (PMID 32326230, 2020). "However, no decrease in DC cytotoxicity was observed after treating two glioblastoma cell lines (GB#10 and GB#13) and U87 cells with rTNF-R1, which indicated that these cell lines were resistant to TNFα-dependent lysis." (PMID 32326230, 2020). "Artificially silencing the expression of H2AFJ predominantly repressed the mRNA levels of TNF-alpha and interleukin-6 in D54MG glioblastoma cells, whereas the forced gene expression of ectopic H2AFJ dramatically enhanced the expression of TNF-alpha and interleukin-6 in T98G glioblastoma cells." (PMID 31906036, 2019). "TNF-α levels had increased significantly in Glioblastoma multiform (p= 0.03)." (PMID 31653130, 2019). "Moreover, TGF-β–induced endogenous Smad2/3 activity was prolonged in TNF-α–treated glioblastoma cells, which suggests that TNF-α sustained TGF-β–induced TGF-β/Smad activation in glioblastoma cells." (PMID 25971746, 2015). "Thus, the current study demonstrates for the first time that Smac mimetic BV6 and Drozitumab synergize to trigger apoptosis in a RIP1-dependent, but TNFα-independent manner in glioblastoma cells." (PMID 25880091, 2015). "Furthermore, Smad luciferase reporter activity was significantly increased in TNF-α–treated glioblastoma cells, as expected." (PMID 25971746, 2015). "Interestingly, there was a marked increased in miR-148a expression in glioblastoma cells treated with tumor necrosis factor-α (TNF-α), whereas TGF-β had minimal effects on miR-148a expression." (PMID 25971746, 2015). "TNF-α is a growth promoting cytokine, which determines the outcome of glioblastoma." (PMID 25182732, 2014). "Additionally, glioblastoma tumor in young patients showed an increased TNF signaling (p<0.05) and protein translational activities (p<0.03), as indicated by the formation of translation initiation complex involving 43S unit." (PMID 23658659, 2013). "These could act in paracrine fashion alone or in combination to suppress glioblastoma cell growth such as described for synergistic inhibitory effect of TNF-α and IP-10 (CXCL10)." (PMID 20509882, 2010). "TNFα has also been shown to induce angiogenesis in malignant glioblastoma cells, highlighting its critical role in tumor progression in GBM." (PMID 40497976, 2025). "Further investigation is needed to fully understand the implications of increased TNF-α expression and to determine how its modulation might be leveraged in developing novel therapeutic strategies for glioblastoma, possibly by harnessing inflammatory responses to enhance treatment efficacy." (PMID 39398744, 2024). "Additionally, since cytokine secretion by CAR-T cells targeting cancer cells indicates T cell activation and specific cytotoxicity, the levels of the classic cytokines (IFN-γ, IL-2, and TNF-α) were measured when CAR-T cells were incubated with glioblastoma cells to assess the cytokine profile." (PMID 39877353, 2024).
glioblastoma (continued). "The expression profile of NF-κB p65 (RelA) and TNFα in GBM patients was studied using the TCGA database and biopsy samples from glioblastoma patients who underwent surgery." (PMID 37892820, 2023). "Interestingly, in glioblastoma, TNFα induces tumor cell motility and invasion via activating NF-κB." (PMID 37892820, 2023). "For instance, engineered mNSCs secrete tumor necrosis factor apoptosis-inducing ligand to the tumor cavity of glioblastoma (GBM)-bearing mice." (PMID 35463812, 2022). "Hence, reduced mTNFα expression on IFN-DCs from glioblastoma patients could be a key factor responsible for the impaired cytotoxic DC function against tumor cells sensitive to TNFα/TNF-R1-dependent lysis." (PMID 32326230, 2020). "Heat shock protein, crystallin alpha B (CRYAB) has also been described to be released from glioblastoma multiforme (GBM) derived-exosomes in response to exposure to pro-inflammatory cytokines IL-1β and TNF-α, to exert an anti-apoptotic activity." (PMID 31555295, 2019). "Generally, TNF-α induces the inflammation, but the concentrated TNF-α can kill the cancer cells in vivo in the glioblastoma." (PMID 40169858, 2025). "For example, TNF-α rapidly phosphorylates p38 MAPK via the TAK1-MKK3/6 cascade, inducing apoptosis in glioblastoma cells." (PMID 41450917, 2025). "It showed pharmacological anti-inflammatory and anti-invasive effects on two aggressive in vitro cancer cell models, the U87 glioblastoma and MDA-MB-231 TNBC cells, against four different pro-inflammatory cues (ConA, PMA, TNFα and TGFβ)." (PMID 40248812, 2025). "We observed similar results for IL-2– and IL-7–expanded glioblastoma patient CD8+ T cells in terms of CD107aHi degranulation, IFN-γ, and tumor-necrosis factor-alpha (TNF-α) production." (PMID 40244705, 2025). "We show that patient-derived glioblastoma cells are capable of autocrine/paracrine TNFα-TNFR1 dependent cell death, identifying TNFR1, TNFα and NFκB as key targets in this pathway." (PMID 38212807, 2024). "In athymic mice implanted with human glioblastoma cells intracranially, the co-administration of HSV-1 with anti-TNFα increased mouse survival." (PMID 39196415, 2024). "Patient-derived glioblastoma cells were pre-treated with 1 (100 nM) or vehicle (0.01% DMSO) for 24 h, followed by TNFα (50 μg/mL, 15 min) or vehicle (0.1% BSA/PBS, 15 min)." (PMID 38212807, 2024). "As exemplified by the case of our mesenchymal GBM sLCRs, those reporters were highly induced by TNF-alpha in GBM cells, confirming that they are functional but lowly expressed in transient transfection of non-glioblastoma cells, supporting their specificity." (PMID 38316783, 2024). "In an immunocompetent glioblastoma model treated with HSV, the administration of TGFβ decreased TAM infiltration and their TNFα and NOS2 expression." (PMID 39196415, 2024). "Upon desialylation of the glioblastoma cells, this induction of CD163 was hampered, and furthermore, the monocytes were now able to secrete higher amounts of IL-6 and TNFα compared to fully sialylated glioblastoma cells." (PMID 39065651, 2024). "CAR133-T cells were significantly proliferative after co-culture with CD133-expressing glioblastoma (GBM) cells, leading to an increase in tumor necrosis factor α (TNF-α) and interferon γ (IFN-γ) levels." (PMID 37446085, 2023). "In a study of glioblastoma (GBM) treated with oHSV, macrophages, and microglia were found to be the main producers of TNF-α, which inhibits viral replication." (PMID 37993941, 2023). "The concentrations of IL-1β, IL-6, IL-8, IL-10, TNFα, and HMGB1 confirmed that inflammation was a critical component of glioblastoma progression." (PMID 38003396, 2023). "Ex vivo gas plasmas exposure of patient-derived primary glioblastoma tissue led to significantly decreased release levels of b-NGF, IL-6, sTREM2, TGF-β, TNF-α, and TREM-1." (PMID 35159079, 2022).
glioblastoma (continued). "We transduced 3D cultures of the human primary glioblastoma GBM001 spheres with targeted RGD4C.TPA.TNFα or RGD4C.TPA.TNFαIL2 and measured the concentration of TNFα in the media using ELISA." (PMID 35758207, 2022). "Similar mechanisms are found in glioblastoma, where EGFR inhibition induces secretion of tumor necrosis factor alpha (TNFα), which subsequently activates JNK, ERK, and AXL RTK." (PMID 32046099, 2020). "SMs synergised with immune checkpoint inhibitors to promote tumour immunity against glioblastoma, an effect that was dependent on both CD8+ T cells and TNF." (PMID 31947615, 2020). "Another cell-death mechanism induced by cannabidiol treatment has been reported, specifically that TNF/TNFR1 and TRAIL/TRAIL-R2 signaling are upregulated and PI3K-AKT/IKK-NF-κB signaling is suppressed in glioblastoma." (PMID 31075907, 2019). "Consistent with this previous finding, two glioblastoma lines that are refractory to combined treatment with SMC and TNF-α or VSVΔ51ΔG were killed upon silencing of cFLIP." (PMID 28198370, 2017). "The addition of Enbrel, a soluble TNFα-blocking antibody, did not inhibit the combination treatment-induced apoptosis in several glioblastoma cell lines, whereas Enbrel blocked apoptosis upon treatment with BV6 and TNFα, which was used as a positive control." (PMID 25880091, 2015). "Interference with ATF3-levels protected cells from apoptosis induction, e.g. induced by TNFα in HUVEC, by cisplatin in a human glioblastoma cell line, or related to doxorubicin in cardiomyocytes." (PMID 25590623, 2015). "However, low expression levels of miR-329 correlate with survival in glioblastoma multiforme patients, studies of hippocampal neurons suggest it to be involved in dendritic outgrowth, and miR-329 expression is decreased in airway smooth muscle treated with IL-1β, TNFα, and IFNγ." (PMID 24143215, 2013). "We demonstrated that these glioblastoma cells were put into relatively cytokine "rich" environment produced by AT-MSC containing IL-1β, IL-1ra, IL-2, IL-4, IL-6, IL-8, TNF-α, IFN-γ, CCL5, CCL26, CXCL10, PDGF-bb." (PMID 20509882, 2010). "Glioblastoma (GBM) is an aggressive IDH wild-type tumor with recurrent molecular alterations; however, comprehensive genomic analyses of GBM arising in patients treated with TNF-α inhibitors are extremely limited." (PMID 42130630, 2026). "This reduction in tumor necrosis factor alpha (TNF‐α), a major regulator of inflammatory responses, may benefit glioblastoma patients by decreasing glutamate release from GBM cells, given the positive correlation between glutamate and TNF‐α." (PMID 40014265, 2025). "Similarly, interactions between PTX3 and inflammatory pathways, including the IL-17 and tumor necrosis factor (TNF) pathways, were identified in a glioblastoma study." (PMID 39594709, 2024). "It is suggested that H2A.J may act similarly as in glioblastoma through upregulating IL-6/STAT signaling, EMT signaling and TNF-α/NF-κB pathways to control inflammatory response, cell proliferation, migration, anti-apoptosis, and survival response." (PMID 38542118, 2024). "Simultaneously, TGF‐β could induce glioblastoma mesenchymal transition through upregulation of CLDN4 and nuclear translocation to activate TNF‐α/Nuclear Factor Kappa‐B (NF‐κB) signal pathway." (PMID 38629624, 2024). "Given TNFα was specifically secreted by glioblastoma cells treated with 1 but not palbociclib, we investigated the role of TNFα in the context of the death receptor TNFR1." (PMID 38212807, 2024). "In relation to the role of NF-κB in cancer, it has been reported to be pro-apoptotic in the anti-tumor action of cisplatin in head and neck squamous cell carcinoma, in glioblastoma in TRAIL-induced cell death, and in adenocarcinoma cells infected with retroviruses or stimulated with TNF-α." (PMID 38203419, 2023).
glioblastoma (continued). "No significant alteration on the concentration of TNF-α and IL-1β in the culture medium of mNPCs with/without glioblastoma-derived EVs treatment was detected using ELISA." (PMID 35022057, 2022). "However, CXCR4-blockade in combination with anti-PD-1 has been shown to have a synergistic effect in increasing the proportion of IFNγ+ and TNFα+ producing CD4+ and CD8+ T cells in the brains of mice with glioblastoma." (PMID 35464424, 2022). "In addition, TNIP1 signalling cascade components, including TNF‐α, TNF receptor and three IκB subunits, were significantly up‐regulated in glioblastoma tissue compared with normal brain tissue." (PMID 31691497, 2020). "In previous experiments with human glioblastoma cells and alveolar epithelial cells, we found that TNFα and IL-1β, respectively, did not induce IDO1 directly, but required IFN-γ to synergistically induce IDO1." (PMID 31267172, 2019). "A combinatorial approach using Smac mimetics together with innate immune stimulants and immune checkpoint inhibitors was shown to result in durable responses in mouse glioblastoma models, which was dependent on cytotoxic T-cell activity, type I IFN, and TNFα signaling." (PMID 29371590, 2018). "Also, a small-molecule Smac mimetic of Smac binding to XIAP, cIAP1 and cIAP2 has been described to synergize with TNFα or TRAIL to induce caspase activation and apoptosis in human cancer cells including glioblastoma cells." (PMID 29371590, 2018). "We show here that cultured and primary glioblastoma cell lines are killed with SMC when combined with exogenous TNF-α, the oncolytic virus VSVΔ51 or with an infectious but non-replicating virus, VSVΔ51ΔG." (PMID 28198370, 2017). "Glioblastomas are characterised by a high level of angiogenesis, and both VEGF secretion from tumour cells and TNF-alpha-induced NF-κB activation in endothelial cells promote endothelial cell survival by increasing anti-apoptotic gene expression under conditions of serum starvation." (PMID 23039130, 2012). "Interestingly, cytokine secretion by CD276-targeted CAR NK-92 cells was more pronounced after co-incubation with non-malignant cell lines and K562 cells, whereas all glioblastoma cells only led to moderate TNFα and IFNγ secretion." (PMID 40469103, 2025). "Our analysis suggests that tumor microenvironment cues such as the growth factors TGFβ and TNFα may be involved in glioblastoma mesenchymal transitions but do not drive a uniform PMT." (PMID 38337036, 2024). "We previously reported that proinflammatory cytokines, particularly tumor necrosis factor (TNF)-α, promoted tumor migration, invasion, and proliferation, thus worsening the prognosis of glioblastoma (GBM)." (PMID 38068712, 2023). "Molecular markers of glioblastoma such as methylated O6-methylguanine-DNA methyltransferase (MGMT) promoter methylation was seen in 16 out of the 33 patients evaluated (48%) and expression of immunological markers such as TNF-a, IL-1β, and IL-6 was considered in one patient." (PMID 38137175, 2023). "Interestingly, inhibition of paracrine/autocrine TNFα signaling has been found to rescue HT-29 colon carcinoma cells, but not A172 glioblastoma cells from IFNα/Smac mimetic-induced cell death." (PMID 29371590, 2018).
glioblastoma (continued). "While we did not observe TNF-alpha as anti- or pro-viral in medulloblastoma or ATRT cells, it is antiviral in ZIKV-infected adult glioblastoma cells." (PMID 40240536, 2025). "Additionally, researchers have investigated the resistance mechanism of bevacizumab in the treatment of glioblastoma (GBM) and found that GBM cells secrete two cytokines, IL-8 and CCL2, which stimulate TAMs to produce TNFα, which activates endothelial cells (ECs)." (PMID 38787372, 2024). "Since no study of TNF-TNFRSF1A and TNFSF12-TNFRSF12A has been reported so far, our study discovered novel glioblastoma-macrophage/microglia interactive patterns." (PMID 36494582, 2023). "We detected significant cytotoxicity against glioblastoma cells and increased levels of IFN-γ, TNF-α, and IL-2 in the presence of anti-CAIX CAR-T cells but not in control T cells." (PMID 31935881, 2020). "We have shown that bevacizumab, but not the TNFα antagonist infliximab, also exhibits marked ADCC activity against human glioblastoma cells in vitro." (PMID 33178180, 2020). "Human brain tumor cells, such as malignant glioma like or glioblastoma multiforme, express CD70, and this CD70 – but not TNFα or FasL – initiated T-cell death through the receptor-dependent pathway." (PMID 23692980, 2013). "Imaging studies are routinely done to evaluate tumor response serially over time in glioblastoma patients, so tumor size and metabolism could be measured in concert with an AAVP delivering TNF, but not gene expression itself." (PMID 31130731, 2020). "When the effect of CRT on IFN-γ, IL6, and TNFα was investigated for patients with locally advanced non-small-cell lung cancer (NSCLC) or glioblastoma multiforme (GBM), TNF-α levels in NSCLC and IFN-γ levels in GBM decreased." (PMID 38534922, 2024).